RPL5 (ribosomal protein L5)
Diseases named in the same sentence as RPL5 in open-access papers (continued):
Sharing a sentence is not in itself a finding about the gene and the disease.
cancer (61 papers, 2010 to 2025). A tumor composed of atypical neoplastic, often pleomorphic cells that invade other tissues. "A study of nearly 8000 patients with 16 different cancer types showed that RPL5 is one of the main RPs mutated in numerous cancers." (PMID 40940922, 2025). "Among the 34 RPs exhibiting an increased ratio in cancer, missense mutations in RPL11 and RPL5 occur in 73% and 66% of the 19,000 cancer samples across 49 cancer types." (PMID 39086661, 2024). "RPL5 has been noted to be a tumor suppressor gene, and downregulation of the gene has been associated with cancer recurrence and poor prognosis." (PMID 36497424, 2022). "Most interestingly, both RPL11 and RPL5 present inactivating mutations and emerge as candidate cancer drivers in the same cancer type (SKCM)." (PMID 28147343, 2017). "The RPL5 gene, crucial to ribosome biogenesis, is linked to various cancers." (PMID 38255260, 2024). "In total, 139 RPL5 mutations and 74 different cancer-associated RPL11 mutations have been detected across 49 cancer types; these genes were found to be mutated in 34% of breast cancers, 28% of melanomas, and up to 34% of multiple myelomas in a comprehensive analysis of 19,000 cancer samples." (PMID 38255260, 2024). "Downregulation of RPL5 may contribute to poor prognosis, suggesting that RPL5 may be a diagnostic biomarker for human cancers." (PMID 35293275, 2022). "Finally, RPL5 was the only gene with a significantly high mutational frequency according to MutSig 2.0 and the only gene significantly mutated in 2 different cancer types." (PMID 28147343, 2017). "Recurrent mutations in genes of the large 60S subunit components RPL5, RPL10, RPL11, RPL22, and RPL23A, and the small 40S subunit components RPS15, RPS20, and RPS27 have been specifically implicated in cancer." (PMID 40805230, 2025). "Somatic mutations and deletions affecting RPs, such as RPL5, RPL10, RPL22, and RPS15, have been identified across multiple cancer types." (PMID 40427096, 2025). "Analysis of 19,000 cancer samples from The Cancer Genome Atlas (TCGA) and International Cancer Genome Consortium (ICGC) revealed mutations in RPL5 and RPL11 in 139 and 74 cases, respectively, indicating their involvement in cancer pathogenesis." (PMID 40805230, 2025). "While RPL22 is mutated in cancer and clearly implicated in MDM4 splicing, what is the evidence regarding RPL5 and RPL11 in cancer?" (PMID 40427096, 2025). "We found that the expression of RPL5 was increased, while HLA-A was downregulated along cancer invasion in clinical CRC samples using immunohistochemical staining." (PMID 36816947, 2023).
cancer (continued). "Immunohistochemical staining in clinical CRC tissues showed that the expression of RPL5 was increased, while HLA-A was downregulated along cancer invasion." (PMID 36816947, 2023). "The pan-cancer gene expression patterns were performed to examine the differential expression of RPL5 across TCGA cancer types." (PMID 36384455, 2022). "Numerous studies have reported that RPL5 was involved in the progression of various malignant tumors." (PMID 36384455, 2022). "Numerous studies have reported that RPL5 is involved in the progression of various malignant tumors." (PMID 36384455, 2022). "A total of 79 genes were found to have significant effects on prognosis based on their expression, and 23 genes had significant impacts on prognosis in at least two different cancer types, including C1R, RPL5, and TERT." (PMID 36497424, 2022). "The results showed that the expression level of RPL5 was up-regulated in tissues of most cancer types, including COAD, compared with corresponding adjacent tissues." (PMID 36384455, 2022). "Heterozygous RPL5 and RPL11 mutations or deletions have been identified in spontaneous human cancer." (PMID 34462428, 2021). "Recently, several RPs, including RPL5, RPL11, and RPS14, have been found to associate with TAp73, but not ΔNp73, to overcome MDM2-mediated inactivation, leading to TAp73-induced cancer cell apoptosis." (PMID 32198344, 2020). "Two significantly deregulated cancer-related genes, RPL5 and RPL10, showed outstanding performance in the ROC analysis." (PMID 30479569, 2018). "A recent study identified six ribosomal protein genes as potential cancer drivers in five different cancer types: uL18/RPL5, uL5/RPL11, uL23/RPL23A, uS7/RPS5, uS10/RPS20, and uS2/RPSA82." (PMID 29674660, 2018). "Among the key cancer-related PCGs in the co-expression network, RPL5 and RPL10 showed high levels of sensitivity and specificity AT/RT and KRT." (PMID 30479569, 2018). "Whereas somatic mutations in RPL5 had been described in 3% of GBM samples, we found that RPL5 heterozygous inactivation currently represents the most common somatic ribosome defect in human cancer." (PMID 28147343, 2017). "We screened mutation and copy number data of respectively 4926 and 7322 samples from 16 cancer types and identified six altered genes (RPL5, RPL11, RPL23A, RPS5, RPS20 and RPSA)." (PMID 28147343, 2017). "According to these criteria, five genes (RPL5, RPL11, RPS5 (uS7), RPS20 (uS10), RPSA (uS2)) were significantly mutated in four different cancer types." (PMID 28147343, 2017). "Our screening for mutations and copy number changes identified six ribosomal protein genes as candidate cancer driver genes, including RPL5 and RPL11, which were previously reported in cancer." (PMID 28147343, 2017). "RPL5 was upregulated, while HLA-A was downregulated along cancer invasion in CRC samples." (PMID 36816947, 2023).
cancer (continued). "DBA variants in patients with cancer/MDS refer mainly to RPS19, RPL35A, RPL11, RPL5, RPS17, and GATA1 genes (18%, 13%, 10%, 5%, 3%, and 3%, respectively; 49% unknown)." (PMID 38002903, 2023). "Data from TCGA and GTEx databases were used to analyze the RPL5 expression in pan-cancer." (PMID 36384455, 2022). "Previous evidences demonstrate that c-Myc and its regulated ribosomal biogenesis by ribosomal RNA synthesis and processing are critically involved in cancer progression and ribosomal protein L5 (RPL5), RPL11, and RPL23 regulates apoptosis in response to ribosomal stress." (PMID 31574980, 2019). "As such, RPL5 inactivation currently represents the most common somatic ribosome defect in cancer." (PMID 28147343, 2017). "We describe the first models for heterozygous RPL5 inactivation in cancer cell context." (PMID 28147343, 2017). "RPL5 emerged as the strongest candidate cancer driver gene from our analysis." (PMID 28147343, 2017). "RPL5 was the strongest candidate cancer gene emerging from our screening." (PMID 28147343, 2017). "RPL11 and RPL5 may inhibit cancer cell proliferation and induce apoptosis." (PMID 32483207, 2020). "The co‐IP assays revealed that BRIX1 bound to both RPL5 and RPL11 in cancer cells when treated with Act D." (PMID 39475053, 2024). "The expression of STC1, AKR1B1, RPL5, and CD47 was increased, while HLA-A was downregulated along cancer invasion by immunohistochemical staining in clinical samples." (PMID 36816947, 2023). "RPL5 was heterozygously deleted in 8.4% of GBM and 25.3% of SKCM patients and in both cancers the RPL5 gene locus was positioned in a distinct focal peak of deletion." (PMID 28147343, 2017).
cancer (continued). "The mutation of RPL5 that we report here, the G201D substitution, has never been described before, not only in T-ALL, but in general in human cancer." (PMID 36482893, 2022). "Interestingly, LIN28A is associated with specific ribosomal proteins in an RNA-independent mode, and several of these proteins, such as RPL5, RPL10, and RPS27L, have been shown to promote tumorigenesis or cancer." (PMID 34816099, 2021). "In this cancer type, also c-MYC amplification co-occurred with RPL5 inactivation." (PMID 28147343, 2017). "We found lots of them might play a key role in the transformation of enterocyte progenitor cells to cancer cells such as MALAT1, B2M, EEF1A1, RPL5, B3GNT7, RHOB and ACTB might play a key role in the transformation of enterocyte progenitor cells to cancer cells." (PMID 36944972, 2023). "RPL5 promoted colon cell proliferation and migration, at least in part, by activating the MAPK/ERK signaling pathway, which may serve as a novel therapeutic target for cancers in which MAPK/ERK signaling is a dominant feature." (PMID 36384455, 2022).
infection (10 papers, 2008 to 2025). The state of being infected such as from the introduction of a foreign agent such as serum, vaccine, antigenic substance or organism. "This study chose the ribosomal protein L5 gene to design a DNA vaccine against the infection with L. tropica which is the causative agent of major cutaneous cases in Syria." (PMID 34094593, 2021). "Nonetheless, these data overwhelmingly support that Bif are enriched in NVL, RPL5, and both Nyx effectors during infection." (PMID 36609656, 2023). "Upon PSTVd infection, the expression of RPL5 is induced about 2-fold." (PMID 30227597, 2018). "HCT-116 infection with RPL27A-sh2 induced significant increases in cells at the early stage of apoptosis (55%), as was the case with RPS14 (40%) and RPL5 (35%) knockdown." (PMID 27374104, 2016). "No co-localisation of LAMP1 was observed with either NVL or RPL5 at 48 h post-infection nor with 4HA or 3FLAG-tagged NyxA, suggesting the absence of autophagosome formation." (PMID 36609656, 2023). "The formation of these cytoplasmic structures was also dependent on the Nyx effectors as a strain lacking both NyxA and NyxB showed a reduced number of RPL5-positive foci at 48 h post-infection." (PMID 36609656, 2023). "Consistently, we did not observe any significant co-localisation between translocated 3FLAG-NyxA and LC3 nor with NVL or RPL5 at 48 h post-infection, using cells expressing LC3-GFP to avoid methanol fixation." (PMID 36609656, 2023). "Although the true receptor for RSV had not yet been identified, our results suggested that three ribosomal proteins (RPL5, RPL7a and RPL8) might play potential crucial roles in the infection and propagation of RSV in vector cells." (PMID 22028913, 2011). "Additionally, the ribosomal protein L5 gene was non-significantly up-regulated by infection in cones of all the cultivars: Saaz (2.7 times), Sládek (4.3 times), Premiant (9.5 times), and Agnus (9.4 times)." (PMID 34834660, 2021).
RPL5 also shares sentences with these, for which no sentence is quoted: endometrial cancer (5 papers); glioma (5); myelodysplastic syndrome (3); bone marrow failure (2); chronic lymphocytic leukemia (2); HCMV infection (2); lung adenocarcinoma (2); lymphoma (2); pancreatic cancer (2); adult T-cell acute lymphoblastic leukemia (1); autoimmune disease (1); B-cell lymphoma (1); Barrett esophagus (1); basal cell carcinoma (1); bladder cancer (1); Bloom syndrome (1); chronic myeloid leukaemia (1); coloboma (1); cutaneous melanoma (1); diabetes mellitus (1); dyskeratosis congenita (1); esophageal cancer (1); fungal keratitis (1); gastric cancer (1); genetic disorders (1); hematologic malignancies (1); Hypertension (1); Intellectual disability (1); nerve sheath tumors (1); neurological diseases (1).
A further 13 diseases each share a sentence with RPL5 in 1 paper.